MIR598 (microRNA 598)
Synonyms: hsa-mir-598; MIRN598; mir-598
Gene: MicroRNA gene on chromosome 8 (11,035,206 to 11,035,302, reverse strand). Ensembl gene ENSG00000207600.
Gene Ontology:
Cellular component: RISC complex
Homologues: Orthologues: chimpanzee ptr-mir-598 (100% identical), macaque MIR598 (100% identical), guinea pig MIR598 (77% identical), rat Mir598 (76% identical), mouse Mir598 (75% identical).
Diseases named in the same sentence as MIR598 in open-access papers:
MIR598 is named in the same sentence as 1 disease in open-access papers, as found by Europe PMC text mining. Sharing a sentence is not in itself a finding about the gene and the disease.
MIR598 shares sentences with these, for which no sentence is quoted: autism spectrum disorder (1 paper).